SFTPA2 (surfactant protein A2)
Description:
In presence of calcium ions, it binds to surfactant phospholipids and contributes to lower the surface tension at the air-liquid interface in the alveoli of the mammalian lung and is essential for normal respiration.
Synonyms: PSP-A; PSPA; SP-A; SP-A2; COLEC5; PSAP; SFTP1; SFTPA2B; ILD2; SP-2A; SPA2; SPAII
Tractability: Antibody: UniProt places it where antibodies can reach, with high confidence; its Gene Ontology location is reachable by antibodies, with high confidence; UniProt predicts a signal peptide or a membrane-spanning region.
Gene: Protein-coding gene on chromosome 10 (79,555,761 to 79,560,492, reverse strand). Ensembl gene ENSG00000185303.
Subcellular location: Secreted; Secreted, extracellular space, extracellular matrix; Secreted, extracellular space, surface film
Pathways (Reactome):
Disease: Defective CSF2RA causes SMDP4; Defective CSF2RB causes SMDP5; Defective SFTPA2 causes IPF
Immune System: Regulation of TLR by endogenous ligand; Toll Like Receptor 4 (TLR4) Cascade; Toll Like Receptor TLR1:TLR2 Cascade
Cell-Cell communication: Signal regulatory protein family interactions
Metabolism of proteins: Surfactant metabolism
Gene Ontology:
Molecular function: protein binding
Cellular component: extracellular region; clathrin-coated endocytic vesicle; endoplasmic reticulum membrane; lamellar body; multivesicular body
Genetic constraint (gnomAD): Loss-of-function variants: 21 observed, 20.73 expected, observed/expected ratio (o/e) 1.01, 90% interval 0.72 to 1.46. The upper end of that interval is the gene's LOEUF score, 1.46, which puts it in group 6 of 6, group 1 being the genes least tolerant of losing a copy. Missense variants: 302 observed, 305.46 expected, observed/expected ratio (o/e) 0.99, 90% interval 0.9 to 1.09. Synonymous variants: 116 observed, 115.89 expected, observed/expected ratio (o/e) 1, 90% interval 0.86 to 1.17.
Gene-disease validity (ClinGen):
ClinGen rates the evidence that SFTPA2 causes each of these diseases.
interstitial lung disease 2 (autosomal dominant): Definitive.
Homologues: Orthologues: chimpanzee SFTPA2 (98% identical), macaque SFTPA1 (91% identical), pig SFTPA1 (76% identical), rabbit SFTPA1 (75% identical), rat Sftpa1 (71% identical), guinea pig Sftpa1 (71% identical), mouse Sftpa1 (71% identical), tropical clawed frog sftpa (49% identical). Paralogues in human: SFTPA1 (97% identical), SFTPD (40% identical), COLEC10 (27% identical), COLEC11 (27% identical).
Diseases named in the same sentence as SFTPA2 in open-access papers:
SFTPA2 is named in the same sentence as 51 diseases in open-access papers, as found by Europe PMC text mining. Sharing a sentence is not in itself a finding about the gene and the disease. The quoted sentences say what the papers report.
lung carcinoma (28 papers, 2012 to 2026). "Pathogenic variants in SFTPA1 and SFTPA2 are also associated with lung malignancy, like in this case, with the risk of lung cancer in this group estimated to be as high as 36% as compared to 13% for individuals with IPF." (PMID 38461429, 2024). "Studies have shown that SFTPA2(Surfactant Protein A2) mutations are associated with interstitial lung disease and lung cancer, but its role in other tumors, including prostate cancer, requires further study." (PMID 36439479, 2022). "It has been shown that a rare missense mutation in SFTPA2 can cause idiopathic pulmonary fibrosis and lung cancer." (PMID 35524179, 2022). "The familiar forms of PF include ILD2 (OMIM #178500), a disease related to SFTPA2 mutations and characterized by pulmonary fibrosis, interstitial pneumonia and lung cancer." (PMID 36553114, 2022). "Among the six LUAD-SDGs, surfactant protein A including SFTPA1 and SFTPA2 were reported closely associated with lung cancer." (PMID 29152081, 2017). "Although PF is known to increase the risk of lung cancer, this association should strongly recommend a molecular screening for SRG, especially SFTPA1 and SFTPA2, which have recently been shown to be associated with a high risk of lung cancer, particularly in smokers." (PMID 41041870, 2026). "We found four proteins associated with cancer that in observational long time-to-diagnosis analyses, and cis-pQTL and exGS analyses; CD74 and TNFRSF1B were associated with NHL, and ADAM8 and SFTPA2, were associated with risk of leukaemia and lung cancer, respectively." (PMID 38750076, 2024). "In detail, variants in the SFTPA2 gene (the surfactant protein A) are associated with ER stress and an increased risk of developing lung cancer in smokers; those in the SFTPC gene (the surfactant protein C) lead to a misfolded SP-C, which thus accumulates in the ER, causing ER stress." (PMID 36553114, 2022). "In the paper, the authors demonstrated that SFTPA2 encodes surfactant protein A that plays a vital role in maintaining normal lung function and has been implicated in various lung diseases, which can accurately distinguished lung cancer from other cancer samples." (PMID 34149811, 2021). "In instances where an association with ILD/PF and lung cancer was reported, all patients with a positive molecular diagnosis exhibited SFTPA1 or SFTPA2 variants (n = 4)." (PMID 41041870, 2026). "Lung cancer develops in up to one third of patients carrying SFTPA1 and SFTPA2 germline mutations, suggesting an increased risk of lung cancer." (PMID 37893169, 2023). "Pathogenic mutations in SFTPA1 and SFTPA2 have been mainly linked to FPF cases and they usually also associate with lung cancer in adult patients." (PMID 37181377, 2023). "Mutations in SFTPA2 and SFTPA1 have been reported only in adults and they are considered a recognized cause of IPF and lung cancer." (PMID 37181377, 2023). "Among the lung cancer DCB genes, many are associated with surfactant proteins (e.g., SFTA3, SFTPA2, SLC34A2, and BPIFA1), which function to lower surface tension at the air/liquid interface in alveolar cells." (PMID 33883548, 2021). "A lung cancer-specific gene signature, containing SFTPA1 and SFTPA2 genes, accurately distinguished lung cancer from other cancer samples, the predictive accuracy of LOOCV for TCGA and GSE5364 data were 95.68% and 100%, respectively." (PMID 26292924, 2015). "Surfactant proteins have been extensively studied in relation to various lung diseases, and surfactant protein A2, surfactant protein B and surfactant protein D have been studied as serum lung cancer or lung disease biomarkers." (PMID 22515324, 2012). "Polymorphisms of SFTPA1 and SFTPA2, indeed, predispose to IPF through ER stress and consequent alterations in APC type 2, whilst pathogenetic variants of SFTPA2 are responsible for ILD2, an autosomal dominant condition characterized by a strong genetic predisposition to lung cancer." (PMID 36553114, 2022).
lung carcinoma (continued). "In addition, they found a lung cancer-specific gene signature, containing SFTPA1 and SFTPA2 genes, that was able to distinguish lung cancer from the other cancers." (PMID 34570764, 2021). "The differential regulation of the methylation status of specific CpGs in SFTPA1 and SFTPA2 maybe one of the epigenetic processes that does not only apply to lung cancer but also to other health states." (PMID 34917085, 2021). "Moreover, the level of SFTPA2 mRNA and protein were reduced in lung cancer whereas the mRNA level of DNA methyltransferases (DNMT1 and DNMT2) was increased." (PMID 34917085, 2021). "Methylation of the SFTPA2 promoter represents a potential biomarker for lung cancer diagnosis." (PMID 32286381, 2020). "Interestingly, YWHAB was also shown to interact with surfactant protein A2 (SP-A2) and genetic variants of YWHAB can predispose individuals to IPF and lung cancer." (PMID 31900205, 2020). "To date, only eight SFTPA2 mutations have been reported in IPF, lung cancer, and ILD patients." (PMID 32602668, 2020). "Finally, through the panel of available differential studies (bulk RNA-Seq or microarray), the user can confirm from additional studies in Expression Atlas that SFTPA2 is downregulated in lung cancers." (PMID 32636365, 2020). "Genetic defects in SFTPA2 were demonstrated closely related to lung cancer." (PMID 29152081, 2017). "Specifically for lung cancer, the highest expression level was observed in the alveolar (gene annotation: CLDN18, SFTPA1, SFTPA2, SFTPC) cell population, and erythroblasts (gene annotation not available) also increased their expression." (PMID 35631632, 2022). "Similarly, this DCB subtype specificity also extends to lung cancer: 4 of the 6 lung DCB genes (CXCL17, SFTA3, SFTPA2, and SLC34A2) were upregulated in the plasma of patients with lung adenocarcinoma compared to those with squamous cell carcinoma." (PMID 33883548, 2021).
pulmonary fibrosis (22 papers, 2012 to 2025). Chronic progressive interstitial lung disorder characterized by the replacement of the lung tissue by connective tissue, leading to progressive dyspnea, respiratory failure, or right heart failure. "Meanwhile, EGCG has demonstrated the ability to inhibit the aggregation of misfolded surfactant protein A2 (SP-A2), proposing a prospective role in mitigating the pathogenesis of lung fibrosis associated with protein aggregation." (PMID 39966334, 2025). "Wang and colleagues identified seven variants in exon 6 of the gene encoding SP-A2 in the sequencing of SFTPA2 from individuals in two families with pulmonary fibrosis." (PMID 39768847, 2024). "Lately, mutations in the SFTPA1 and SFTPA2 have been associated with familiar pulmonary fibrosis and rarely with sporadic IPF." (PMID 37893169, 2023). "With the aid of a proteasome denaturation cascade, EGCG decreases the accumulation of pulmonary fibrosis-associated mutant surfactant protein-A2 (SP-A2), but the proteasomal antagonist MG-132 can counteract the EGCG-mediated aggregate diminution." (PMID 37110167, 2023). "Mutations in genes encoding SP-A, SFTPA1 and SFTPA2 have been so far associated with familiar pulmonary fibrosis and rarely with sporadic IPF." (PMID 37893169, 2023). "Among surfactant proteins variants of surfactant protein C (SP-C), surfactant protein A2 (SP-A2) and surfactant protein A1 (SP-A1) have been associated to familiar pulmonary fibrosis, while they are rare in sporadic IPF." (PMID 34200784, 2021). "A rare mutation of the gene encoding surfactant protein A2 (SP-A2) is associated with the development of familial idiopathic pulmonary fibrosis." (PMID 34208586, 2021). "Mutation in SFTPA2 was rare reported, and we identified a novel pathogenic mutation (p.N207Y) of SFTPA2 gene in idiopathic pulmonary fibrosis (IPF) patients in this study." (PMID 32602668, 2020). "Mutations in SFTPA1 and SFTPA2 are associated with idiopathic pulmonary fibrosis, and (along with SFTPD) play an essential role in surfactant homeostasis and in the defense against respiratory pathogens." (PMID 25961286, 2015). "There are many candidate genes implicated in pulmonary fibrosis, such as IGF-I, IGFBPs, ELMOD2, TERT, TERC, SFTPC, SFTPA2), and MUC5B." (PMID 26447616, 2015). "The implication of genetic polymorphisms in SFTPA2, SFTPC, MUC5B as well as DSP (encoding desmoplakin) as risk factors for pulmonary fibrosis suggest that the integrity of the barrier function is critically important in maintaining lung homeostasis." (PMID 24391588, 2013). "Mutations of surfactant-associated genes, including SFTPA1 (location: 10q22.3), SFTPA2 (10q22.3), SFTPC (8p21.3), SFTPB (2p11.2), ABCA3 (16p13.3) and NKX2.1 (14q13.3)), are the second most frequent forms of pulmonary fibrosis, approximately occurring in 1–5% of familial cases." (PMID 37893169, 2023). "Evidence shows that the expression of surfactant protein A2 mutants (SP-A2, SFTPA2) associated with pulmonary fibrosis induces the production of proteins that cannot be secreted and therefore accumulate in the cytoplasm, leading to protein instability and ER stress." (PMID 35743055, 2022).
lung disease (11 papers, 2012 to 2025). "Several genetic variants have been identified for SFTPA1, SFTPA2, SFTPB, SFTPC, and SFTPD that are associated with pulmonary diseases." (PMID 33469544, 2020). "A number of intergenic interactions that all include SNPs of SFTPB as well as a single intragenic SFTPA1 and SFTPA2 interaction are likely to be markers for mild and moderate/severe pulmonary disease in CF, respectively." (PMID 30333828, 2018). "In this study, we report the novel association of polymorphisms in the human surfactant protein genes SFTPA1, SFTPA2, and their associated haplotypes, with the odds of developing ROP while controlling for GA, oxygen exposure and lung disease in preterm infants." (PMID 41102472, 2025). "Some of these known modifiers are ranked within the top DPMs, including EHF, SFTPA2, and SLC6A14, all previously identified modifiers of lung disease severity in CF." (PMID 33438800, 2020).
idiopathic pulmonary fibrosis (9 papers, 2015 to 2023). Idiopathic pulmonary fibrosis (IPF) is a nonneoplastic pulmonary disease that is characterized by the formation of scar tissue within the lungs in the absence of any known cause. "Notably, patients carrying a SFTPA2 mutation were younger, had longer telomeres and were more likely to have a chest computed tomography inconsistent with usual interstitial pneumonia compared with the remaining patients." (PMID 37410458, 2023). "Sequence variants in genes for surfactant proteins (SFTPC, SFTPA1, SFTPA2, ABCA3), polymorphisms in MUC5B or TOLLIP, and mutations in telomere genes (TERT, TERC, PARN, and RTEL1) are associated with an increased risk of idiopathic pulmonary fibrosis (IPF)." (PMID 36864460, 2023).
acute respiratory failure (6 papers, 2014 to 2023). Life-threatening respiratory failure that develops rapidly. "Multivariate analysis showed that two frequent SFTPA2 missense alleles (rs1965708-C and rs1059046-A) and the SFTPA2 haplotype 1A0 were associated with a need for mechanical ventilation, acute respiratory failure, and acute respiratory distress syndrome." (PMID 24950659, 2014). "In another study comparing children with acute respiratory failure and healthy newborn controls, SNPs in SFTPA1, SFTPA2, and SFTPC were associated with acute respiratory failure and pulmonary dysfunction after hospital discharge." (PMID 35913450, 2022). "As such, these proteins may be early markers of type II pneumocyte dysfunction, impaired surfactant synthesis, and lung damage, as SFTPA2 plasma levels are elevated in patients suffering from acute respiratory failure." (PMID 35839768, 2022). "Finally, the authors identified the SFTPA2 haplotype 1A1 to be protective for a number of indicators (acute respiratory failure, acute respiratory distress syndrome, PaO2/FiO2 ratio, and mechanical ventilation), suggesting that this variant may be examined for future therapy against pandemic H1N1." (PMID 25184962, 2014).
asthma (5 papers, 2006 to 2022). "Unadjusted associations between SNPs from surfactant protein A alleles (SFTPA1,SFTPA2) and respiratory symptomsa during the first year of life for white infants at risk for developing asthma." (PMID 17407567, 2007). "In the present study, we used a candidate gene approach to investigate whether polymorphisms within the SFTPA1 and SFTPA2 genes were associated with wheeze and persistent cough during the first year of life among a prospective birth cohort at risk for developing asthma." (PMID 17407567, 2007).
interstitial lung disease (5 papers, 2020 to 2025). A diverse group of lung diseases that affect the lung parenchyma. "Mutations in the genes encoding SP–A, SFTPA1 and SFTPA2, are associated with interstitial lung disease and increased susceptibility to adenocarcinoma of the lung." (PMID 32493486, 2020).
acute respiratory distress syndrome (4 papers, 2014 to 2022). Progressive and life-threatening pulmonary distress in the absence of an underlying pulmonary condition, usually following major trauma or surgery. "Similarly, a previous association study of SFTPA genetic variants with severity of Influenza A virus showed that the 1A0 of the SFTPA2 was associated with a need for mechanical ventilation, acute respiratory failure, and acute respiratory distress syndrome in an adult population." (PMID 35903101, 2022).
lung adenocarcinoma (4 papers, 2020 to 2025). A carcinoma that arises from the lung and is characterized by the presence of malignant glandular epithelial cells. "Mutations in surfactant protein genes SFTPA1 and SFTPA2 in lung adenocarcinoma impair protein secretion, induce endoplasmic reticulum stress and apoptosis, fostering co-occurrence of PF and LC." (PMID 40625354, 2025).
respiratory distress syndrome (4 papers, 2007 to 2024). "Additional polymorphisms within SFTPA1 and SFTPA2, have been linked to respiratory distress syndrome in infants, severe RSV bronchiolitis, and otitis media." (PMID 33617569, 2021). "Polymorphisms within SFTPA1 and SFTPA2, two functional, highly homologous SFTPA genes have been linked to respiratory distress syndrome in infants, severe RSV bronchiolitis, and otitis media." (PMID 17407567, 2007).
COVID-19 (3 papers, 2020 to 2025). A disease caused by infection with severe acute respiratory syndrome coronavirus 2. "For SFTPA2, expression increased 5.13-fold in the severe group compared to the asymptomatic COVID-19-positive patient group and 50.02-fold compared to the mild group, both changes being highly significant (p < 0.0001)." (PMID 40647689, 2025). "For SFTPA2, the expression was 0.2635 ± 0.1272 in asymptomatic COVID-19-positive individuals, 0.0271 ± 0.0035 in the mild group, and 1.3530 ± 0.7601 in severe cases." (PMID 40647689, 2025). "This study aimed to elucidate the effect of COVID-19 on the lung’s surface tension regulatory system by examining the expression of surfactant protein genes (SFTPA1, SFTPA2, SFTPB, SFTPC, and SFTPD) across different disease severity groups." (PMID 40647689, 2025). "In this study, we compared the expression of SFTPA1, SFTPA2, SFTPB, SFTPC, and SFTPD in blood among asymptomatic, mild, and severe COVID-19 patients to identify patterns related to disease severity." (PMID 40647689, 2025).
bacteremia (1 paper, 2014). "SFTPA2 alleles (rs1965708-C and rs1059046-A) and haplotypes (1A0) predisposing to increased severity were found to be associated with significantly lower PaO2/FiO2 ratios, independent of age, gender, risk factors, secondary bacterial pneumonia, and bacteremia." (PMID 24950659, 2014).
chorioamnionitis (1 paper, 2021). A morphologic finding indicating inflammation of the fetal sac membranes. "Furthermore, the concern for infection in the setting of prematurity and chorioamnionitis sets up the SFTPA1 and SFTPA2 gene products, SP-A1 and SP-A2, as very important molecules for the first line of defense and regulation of various processes of the alveolar macrophage." (PMID 34671583, 2021).
Lung squamous cell carcinoma (1 paper, 2021). "As to LUSC(Lung squamous cell carcinoma), The gene SFTPA2 selected by our method is a protein-coding gene." (PMID 34149811, 2021).
lung tumor (1 paper, 2015). "The expression levels of SFTPA1 and SFTPA2 were much higher in lung tissue samples than in any other tissue samples, moreover, these two genes were strikingly down-regulated in lung tumor tissues as compared to the adjacent nontumor tissues." (PMID 26292924, 2015).
infection (15 papers, 2014 to 2025). The state of being infected such as from the introduction of a foreign agent such as serum, vaccine, antigenic substance or organism. "When severity of infection was evaluated in hospitalized patients (n = 70), we observed that two missense variants at SFTPA2 (rs1965708-C and rs1059046-A) were significantly associated with the need for mechanical ventilation (MV) and with development of ARF and ARDS." (PMID 24950659, 2014). "We studied the role of polymorphic variants at the genes of MBL (MBL2), SP-A1 (SFTPA1), SP-A2 (SFTPA2), and SP-D (SFTPD) in 93 patients with H1N1 pandemic 2009 (H1N1pdm) infection." (PMID 24950659, 2014).